CLEC2L (C-type lectin domain family 2 member L)
Synonyms: FLJ32986
Tractability: Antibody: UniProt predicts a signal peptide or a membrane-spanning region. PROTAC: its protein half-life has been measured.
Gene: Protein-coding gene on chromosome 7 (139,523,685 to 139,544,985, forward strand). Ensembl gene ENSG00000236279.
Subcellular location: Membrane
Gene Ontology:
Cellular component: membrane
Genetic constraint (gnomAD): Loss-of-function variants: 14 observed, 19.31 expected, observed/expected ratio (o/e) 0.73, 90% interval 0.48 to 1.13. The upper end of that interval is the gene's LOEUF score, 1.13, which puts it in group 4 of 6, group 1 being the genes least tolerant of losing a copy. Missense variants: 223 observed, 229.34 expected, observed/expected ratio (o/e) 0.97, 90% interval 0.87 to 1.09. Synonymous variants: 94 observed, 93.84 expected, observed/expected ratio (o/e) 1, 90% interval 0.85 to 1.19.
Homologues: Orthologues: chimpanzee CLEC2L (100% identical), macaque CLEC2L (99% identical), pig CLEC2L (95% identical), dog CLEC2L (95% identical), mouse Clec2l (95% identical), rat Clec2l (95% identical), guinea pig CLEC2L (87% identical), rabbit CLEC2L (76% identical), zebrafish si:ch211-170d8.8 (20% identical), Drosophila melanogaster rgn (18% identical), zebrafish si:dkey-26c10.5 (15% identical), Caenorhabditis elegans clec-146 (14% identical), and 2 more. Paralogues in human: KLRG2 (30% identical), CD69 (23% identical), CLEC2D (21% identical), CLEC2A (20% identical), KLRG1 (19% identical), OLR1 (19% identical), CLEC12B (18% identical), CLEC2B (18% identical), CLEC7A (18% identical), KLRB1 (18% identical), KLRF1 (18% identical), CLEC12A (18% identical), and 11 more.